CASP8 (caspase 8)
Diseases named in the same sentence as CASP8 in open-access papers (continued):
Sharing a sentence is not in itself a finding about the gene and the disease.
breast invasive carcinoma (4 papers, 2008 to 2026). "We note similarly complex patterns of correlation between both risk- and protective- allele rs3769823 binding proteins in non-melanocytic tissues (GTEx skin, GTEx breast mammary, and TCGA breast invasive carcinoma) and expression of CASP8 as well as FLACC1." (PMID 41542517, 2026). "For example, BCAC reported that common coding variants CASP8 D302H in the gene encoding Caspase 8, and TGFB1 L10P in the gene encoding transforming growth factor-β (TGFβ), in one allele (heterozygote) were associated with significant risk to invasive breast cancer." (PMID 21655367, 2008). "The analysis of the clinical stages of patients with breast invasive carcinoma indicated that the BAX, BCL2L1, CASP8, CASP9, RELA, and NFKBIA gene expression levels were higher in stages 3 and 4 for all BRCA patients, and in stage 4 for BRCA-LumA patients, than in other clinical stages." (PMID 38542508, 2024).
Burkitt lymphoma (4 papers, 2016 to 2020). A rare form of malignant mature B-cell non-Hodgkin lymphoma. "Activation of caspase-8 is of pivotal importance for induction of apoptosis in Burkitt’s lymphoma cells, Hep2, and HeLa cells." (PMID 32456125, 2020). "Caspase-8-mediated cleavage of Bid and relocalization of its cleavage fragment tBid to the mitochondria is necessary for Stx1-mediated apoptosis in Burkitt’s lymphoma cells." (PMID 32456125, 2020). "Cross-linking of Gb3/CD77 on Burkitt’s lymphoma cells leads to activation of caspase-8, indicating that Gb3/CD77 binding also can activate the extrinsic, caspase-dependent apoptosis pathway." (PMID 32456125, 2020). "Activation of caspase-8-dependent signaling pathways is of prime importance for the induction of apoptosis by Stx holotoxins in Burkitt’s lymphoma cells." (PMID 32456125, 2020). "Exposure of the Burkitt’s lymphoma cell line, BJAB, to TRAIL, or HaCaT keratinocytes to CD95L induced receptor-mediated activation of caspase-8, caspase-3, and apoptotic cell death." (PMID 26990987, 2016).
Clear Cell Renal Cell Cancer (4 papers, 2009 to 2024). "The expression levels of MLKL and CASP8 in tumor samples were higher than those in normal tissues in KIRC (Renal Clear Cell Carcinoma), KIRP (Papillary Renal Cell Carcinoma), and BLCA (Bladder Urothelial Carcinoma)." (PMID 37000317, 2023).
dilated cardiomyopathy (4 papers, 2012 to 2025). Cardiomyopathy which is characterized by dilation and contractile dysfunction of the left and right ventricles. "Transgenic mice that express a conditionally cardiac-specific active caspase-8 exhibited a lethal dilated cardiomyopathy." (PMID 22936985, 2012).
endometriosis (4 papers, 2018 to 2025). The growth of functional endometrial tissue in anatomic sites outside the uterine body. "Genome-wide association studies have reported a significant association of endometriosis with chromosomes 2 and 10, which harbor CASP8 and FAS genes respectively." (PMID 30036894, 2018). "Therefore, the present study aims to investigate the association between CASP8 (rs13416436 and rs2037815) and FAS (rs3740286 and rs4064) polymorphisms with endometriosis in Brazilian women." (PMID 30036894, 2018). "Single nucleotide polymorphisms (SNPs) in apoptotic genes, such as those of the Fas cell surface death receptor (FAS) and the caspase-8 (CASP8) genes, may be involved with the development of endometriosis." (PMID 30036894, 2018). "The present study indicated the absence of association between polymorphisms in the CASP8 gene and the risk of developing endometriosis." (PMID 30036894, 2018). "We read with great interest the article by Pissetti et al1 entitled ‘Gene Polymorphisms in FAS (Rs3740286 and Rs4064) Are Involved in Endometriosis Development in Brazilian Women, but not those in CASP8 (rs13416436 and rs2037815),’ published in your journal." (PMID 30352469, 2018).
epilepsy (4 papers, 2023 to 2024). A brain disorder characterized by episodes of abnormally increased neuronal discharge resulting in transient episodes of sensory or motor neurological dysfunction, or psychic dysfunction. "This study is the first to use immunohistochemistry to explore caspase-8 activation in a model of acute epilepsy." (PMID 39194744, 2024).
Glucose intolerance (4 papers, 2016 to 2024). Glucose intolerance (GI) can be defined as dysglycemia that comprises both prediabetes and diabetes. "Induced expression and activation by dimerisation of Caspase-8 in this model resulted in local inflammation and adipocyte death which was accompanied by marked glucose intolerance." (PMID 36175539, 2023). "Collectively, these findings provide evidence that RIPK3 prevents glucose intolerance in obese mice by inhibiting Caspase-8-dependent adipocyte apoptosis in WAT." (PMID 27323669, 2016). "Our data in obese mice suggest that RIPK3 in adipose tissue maintains homeostasis and dampens inflammation by inhibiting Caspase-8-dependent apoptosis of adipocytes, thereby preventing glucose intolerance." (PMID 27323669, 2016). "Additional genetic inactivation of Caspase-8 protected KO mice from glucose intolerance and insulin resistance." (PMID 27323669, 2016). "Genetic inactivation of Ripk3 promotes increased Caspase-8-dependent adipocyte apoptosis and WAT inflammation, associated with impaired insulin signalling in WAT as the basis for glucose intolerance." (PMID 27323669, 2016). "Notably, this study also showed that the loss of caspase 8 in β-cells results in elevated rates of islet cell death and glucose intolerance in aged chow-fed mice in vivo, indicating distinct roles for β-cell caspase 8 under these conditions." (PMID 38842911, 2024). "On the basis of these findings, we next tested whether additional deletion of Caspase-8 in hepatocytes (Caspase-8LPC-KO) could also rescue KO mice from glucose intolerance (RIPK3−/−/Caspase-8LPC-KO)." (PMID 27323669, 2016). "However, whereas full body Caspase-8 deficiency protects RIPK3-deficient mice from HFD-induced inflammation and glucose intolerance, Caspase-8 deficiency in hepatocytes does not." (PMID 36175539, 2023).
heart failure (4 papers, 2017 to 2024). Inability of the heart to pump blood at an adequate rate to meet tissue metabolic requirements. "A study also showed a conclusion that activation of exogenous caspase-8 in mice led to a large number of cardiomyocyte apoptosis, and caused the death of heart failure in mice." (PMID 39650552, 2024). "Thus, we examined the kinetics of caspase-8 (extrinsic cell death pathway) and caspase-3 (intrinsic apoptosis) activation to determine their relationship to the development of heart failure in the absence of Mdm2." (PMID 29267372, 2017).
Hepatic steatosis (4 papers, 2017 to 2025). Steatosis is a term used to denote lipid accumulation within hepatocytes. "Altogether, these results indicate that Caspase-8 depletion considerably improved EtOH-induced hepatic steatosis via decreased FFA uptake." (PMID 29072704, 2017). "Specifically, we demonstrate that Caspase-8 is a crucial key driver of hepatic steatosis but absolutely dispensable for alcohol-induced cell death, due to compensatory crosstalks between the major apoptotic-inducing extrinsic and intrinsic pathways." (PMID 29072704, 2017). "Furthermore, limonin can reduce hepatic steatosis, lipid accumulation, and the expression of p-STAT3/STAT3, caspase-8, and prostaglandin-endoperoxide synthase 2, and improve the inflammatory response of non-alcoholic fatty liver." (PMID 39944619, 2025). "First, ablation of Caspase-8 resulted in reduced alcohol-mediated liver steatosis." (PMID 29072704, 2017). "BPA exacerbated hepatic steatosis in the OVX HBPA group, elevating lipid/collagen deposition with reduced Mttp mRNA and upregulated β-oxidation (Acox1, Acadvl), mitochondrial uncoupling (Ucp2), ER stress (Hyou1, Atf6), and liver injury (Tgfb1, Casp8) genes." (PMID 40475995, 2025).
Hepatitis (4 papers, 2014 to 2022). Inflammation of the liver. "In addition, most of these genes have a risk coefficient greater than 0 (AC008271.1, C11orf53, F2RL2, GBP5, LUCAT1, RP11‐149I23.3, RP11‐383 J24.1 and SLC35G2), except for CASP8 and RP11‐114B7.6, suggesting that these genes are adverse prognostic factors in hepatitis‐positive HCC patients." (PMID 35637633, 2022). "Interestingly, TNFR1 deficiency did not prevent hepatocyte apoptosis, hepatitis and liver tumour development in these mice, suggesting that TNFR1-independent pathways driving caspase-8-mediated apoptosis cause the pathology." (PMID 34625557, 2021).
HIV-1 infection (4 papers, 2008 to 2025). The type species of lentivirus and the etiologic agent of acquired immunodeficiency syndrome (AIDS). "Based on these observations, we wondered whether PR could mimic the role of caspase-8 in attenuating type I IFN signaling by directly cleaving RIPK1 during HIV-1 infection." (PMID 26297639, 2015).
injury (4 papers, 2011 to 2023). Damage inflicted on the body as the direct or indirect result of an external force, with or without disruption of structural continuity. "The activation of caspase-3 and caspase-8 was found in various apoptotic cells, and the upregulation of caspase-3 and caspase-8 was also found in I/R-induced liver injury, indicating that caspase-mediated apoptosis is essensial in organ I/R injury." (PMID 33927775, 2021). "A protective role of caspase 8 deletion in vivo was also demonstrated using a controlled cortical impact (CCI) model of traumatic brain injury (TBI) and seizure-induced brain injury caused by kainic acid (KA)." (PMID 21957448, 2011). "Many studies have shown that inhibiting apoptosis (caspase-3, caspase-8) attenuates kidney injury." (PMID 32626733, 2020). "Autophagy inhibits TNF toxicity by blocking caspase 8 activation and mitochondrial death pathways in vivo, suggesting that autophagy is a potential therapeutic target in the treatment of TNF-α-induced liver injury." (PMID 38129372, 2023).
lymphoproliferative syndrome (4 papers, 2016 to 2025). A disorder characterized by proliferation of lymphocytes at various stages of differentiation. "OTULINL272P/L272Pcasp8−/−RIPK3−/− mice were born in Mendelian numbers and developed normally without any sign of inflammation with the exception of the lymphoproliferative syndrome that develops in Casp8−/−RIPK3−/− mice, as previously shown." (PMID 34625556, 2021). "This increase is thus temporally distinct from the increase in inflammation and in serum cytokines in Casp8−/−Ripk3−/− mice that is found to occur rather late after birth, as a consequence of a lymphoproliferative syndrome that they develop." (PMID 29666472, 2018).
meningioma (4 papers, 2010 to 2024). A generally slow growing tumor attached to the dura mater. "In conclusion, although caspase 8 expression demonstrates different expression patterns in meningiomas, it is associated with differentiation grade and mitotic activity in them." (PMID 35891812, 2022). "Additionally, CASP8 Ex13+51G>C variant seems to influence positively the meningioma development risk." (PMID 35891812, 2022). "Targeted therapeutic strategies focused on enhancing caspase 8 expression and also inducing the overall apoptotic activity should be a very promising approach in rationally handling sub-groups of meningioma patients." (PMID 35891812, 2022). "Interestingly, specific polymorphisms affecting genes such as caspase 8, NF2, XRCC1, and BRIP1 are related to increased risk for meningioma rise." (PMID 35891812, 2022). "Caspase 8 expression was observed in high, moderate, and low levels associated with differentiation grade and mitotic activity of the examined malignancies, but not with meningioma-specific histo-types." (PMID 35891812, 2022). "Similarly, the expression of CA-IX and Bcl-2 members family (regulators of apoptosis in tumor cells) including RTRAIL-R2, RTRAIL-R4, caspase-8, cFLIP, Bak, Bcl-XL, and Mcl-1 did not associate with OS or PFS of meningioma patients (p>0.05)." (PMID 38758750, 2024).
non-alcoholic fatty liver disease (4 papers, 2020 to 2026). "The deficiency of miR-150 in non-alcoholic fatty liver disease resulted in decreased IR through regulation of CASP8." (PMID 32093712, 2020).
osteoarthritis (4 papers, 2019 to 2026). A noninflammatory degenerative joint disease occurring chiefly in older persons, characterized by degeneration of the articular cartilage, hypertrophy of bone at the margins and changes in the synovial membrane. "In RA, caspase-3 activation is reported in monocytes and macrophages, and the dual inhibition of caspase-3 and caspase-8 has alleviated osteoarthritis symptoms in animal models." (PMID 40564127, 2025). "Abrine has the highest affinity for the CASP8 docking pocket and has been shown to inhibit apoptosis of osteoblasts in osteoarthritis through the PIM2/VEGF signaling pathway." (PMID 38439022, 2024).
parasite infection (4 papers, 2014 to 2025). "Finally, some studies aimed to address the magnitude and functional properties of the T cell response after parasite infection of Casp8 (caspase-8)-deficient mice or in the presence of caspase-8 inhibitors." (PMID 24551250, 2014). "In relation to the role of Caspase 8 in the induction of apoptosis by T. cruzi, it has been demonstrated that the Caspase 8 inhibitor zIETD blocks T cell apoptosis in infected mice, and the usage of the pan caspase inhibitor, zVAD, during acute infection reduces splenocyte apoptosis and parasitemia." (PMID 40661785, 2025). "It has also been reported that caspase-8 plays an important role in controlling the transcription of Il12b and Il1b, and mice lacking caspase-8 rapidly succumb to parasitic infection." (PMID 40854593, 2025).
periodontitis (4 papers, 2019 to 2026). An acute or chronic inflammatory process that affects the tissues that surround and support the teeth. "CASP8, which can cleave GSDMD, resulting in pyroptosis activation, has been shown to be expressed at lower levels in aggressive periodontitis as compared to chronic periodontitis." (PMID 35844512, 2022). "Furthermore, rank-sum test analysis in this study revealed differential expression of key PANoptosome components such as RIPK3, CASP8, and CASP1, suggesting that periodontitis may involve ZBP1-mediated PANoptosome formation." (PMID 40612110, 2025).
preeclampsia (4 papers, 2017 to 2024). Preeclampsia is a hypertensive disorder of pregnancy that is characterized by new-onset hypertension with proteinuria presenting after 20 weeks of gestation, and depending on mild or severe forms may initially present with severe headache, visual disturbances, and hyperreflexia. "Likewise, we also recently observed that not only caspase 8 but also caspase 5 were enhanced in the placental tissue of women with late-onset preeclampsia." (PMID 38791563, 2024). "In addition, caspase-8 activity was reduced in severe early-onset preeclampsia cases." (PMID 28151467, 2017). "We found no preeclampsia-related changes in BAP31, CASP8 or BID, which can signal apoptosis through the extrinsic pathway and via the ER." (PMID 30455461, 2018).
retinal degeneration (4 papers, 2019 to 2025). Degeneration of the retina. "The relative mRNA expression of the apoptosis-related genes BAX, BCL2, CASP3, CASP8, and CASP9 was analyzed to study the events associated with the apoptosis process during spontaneous retinal degeneration." (PMID 35221932, 2022). "Key molecules participating in apoptosis (caspase-3 and caspase-8) and necroptosis (RIP3 and MLKL) were activated in infected mice compared to age-matched, uninfected controls, indicating that both apoptosis and necroptosis participate in retinal degeneration during MCMV latency." (PMID 41012634, 2025).
retinoblastoma (4 papers, 2015 to 2025). A malignant tumor that originates in the nuclear layer of the retina. "Based on data from the GEO database and GSEA analysis, we found that in retinoblastoma, caspase-3 is downregulated, while caspase-8 and c-FLIP (cFLAR) are upregulated." (PMID 40309730, 2025). "Similar to previous studies, we found that xanthatin induced cell apoptosis, including both early apoptosis and late apoptosis, in retinoblastoma cells, with significant upregulation of the cleavage of caspase-8, -9, -3, and PARP." (PMID 40309730, 2025). "Poulaki reported that caspase-8 got methylation resulting in gene silencing which decreased expression of caspase-8, and prevented human retinoblastoma cells from apoptosis." (PMID 28454103, 2017). "Western blot results showed that the expression levels of caspase-8, caspase-9, caspase-3, and cleaved PARP increased in a concentration-dependent manner after the treatment of retinoblastoma cells with xanthatin." (PMID 40309730, 2025). "Instead, Caspase-8 and BIK are methylated in the Wery Rb1 cell line, thus implying that up-regulation is due to a direct effect of the agent on the genes (SM MSP Wery cells file), and justifying transcriptional activation and sensitization to apoptosis of retinoblastoma cells." (PMID 26143641, 2015).
thyroid (4 papers, 2011 to 2020). "Our data suggests that aberrant methylation of CASP8, RASSF1, and NIS maybe an early change in thyroid tumorigenesis regardless of cell type." (PMID 21738852, 2011).
Yersinia pestis infection (4 papers, 2021 to 2024). "Likewise, Casp8–/–Ripk3–/– mice were shown to be susceptible to a subcutaneous Yersinia pestis infection but resistant against an intratracheal infection with E. coli." (PMID 37080966, 2023). "For example, mice defective in caspase-8 and/or RIP3 were highly susceptible to Yersinia pestis infection, and caspase-8-mediated cell death overrides blockade of NF-κB and MAPK signaling by the yersinia virulence factor YopJ to promote anti-yersinia immune defense." (PMID 34887869, 2021). "Indeed, recent work by the Brodsky lab indicates that CASP8 can cleave and activate CASP1, and that activated CASP8 can cleave the inflammatory substrates GSDMD, IL-1β, and IL-18 during Yersinia pestis infection in mouse bone marrow-derived macrophages (BMDMs) (73, –, 75)." (PMID 38837391, 2024).
amyloid (3 papers, 2019 to 2023). "Overall, our work positions caspase-8 as a key regulator of amyloidosis and Aβ-mediated microgliosis." (PMID 36602874, 2023). "Interestingly, some CASP8 variants have been previously associated with AD66, and the protein has been shown to be involved in amyloid related pathways and activated in both blood and brain cells from AD patients." (PMID 31723151, 2019). "Taken together, these data suggest that caspase-8 is required for AD progression; however, to our surprise, it does not appear that caspase-8 appreciably affects neuronal cell death in 5xFAD mice, despite playing a substantial role in promoting amyloidosis and microgliosis." (PMID 36602874, 2023).
Anxiety (3 papers, 2022 to 2023). Intense feelings of nervousness, tension, or panic often arise in response to interpersonal stresses. "Animals lacking CASP8 also exhibit anxiety behavior, which is one of the most common co-occurring psychiatric conditions in children with ASD." (PMID 35493109, 2022).
autism (3 papers, 2022 to 2024). Persistent deficits in social interaction and communication and interaction as well as a markedly restricted repertoire of activity and interest as well as repetitive patterns of behavior. "In Drugbank, two potential therapeutic drugs, Acamprosate (GABBR1 inhibitor) and Bryostatin 1 (CASP8 inhibitor), were inferred as potential influencers of autism." (PMID 39038939, 2024). "Insights from embryonic studies on autism suggest early-stage impairments, even during the neural tube phase, where CASP8 may play a role at this profound phenotypic level." (PMID 39038939, 2024).